STAT3 (signal transducer and activator of transcription 3)
Diseases named in the same sentence as STAT3 in open-access papers (continued):
Sharing a sentence is not in itself a finding about the gene and the disease.
ovarian carcinoma (continued). "In ovarian cancer, it regulates self-renewal but also EMT and chemo-resistance via the STAT3 signalling pathway." (PMID 38201468, 2023). "CAFs provide ovarian cancer cells resistance to cisplatin by secreting cisplatin-induced chemokine (C-C motif) ligand 5 (CCL5), which augments the phosphorylation of STAT3 and Akt in cancer cells." (PMID 37065872, 2023). "Glutamine metabolism is one of the hallmarks of ovarian cancer and is known to stimulate the mTOR/MAPK and STAT3 signaling pathways, and inhibition of glutamine metabolism has been shown to provide therapeutic benefits." (PMID 37375634, 2023). "Blocking STAT3 decreased G6PD mRNA expression and increased the sensitivity of paclitaxel resistant ovarian cancer cells to paclitaxel." (PMID 36902166, 2023). "Other in vitro studies based on the use of the STAT3 ODN-decoy in OVCAR3 and SKOV3 ovarian cancer have shown that it inhibited cell proliferation, led to cell cycle arrest, and inducted cell apoptosis." (PMID 38067351, 2023). "The study showed that leptin stimulation led to an increased proliferation, survival and migration of LEPR-expressing ovarian cancer cell lines, with these effects shown to be mediated by the JAK2/ STAT3 pathway." (PMID 37238197, 2023). "In support, ER‐independent IGF‐1R, TGF‐β, JAK/STAT3, MAPK/ERK and PI3K/Akt were also previously reported to mediate BPA actions in ovarian cancer cells." (PMID 37610061, 2023). "Studies have indicated that prosurvival signaling, such as AKT, STAT3, ERK, and p38 MAPK is one of the crucial mechanisms of paclitaxel in ovarian cancer." (PMID 38137377, 2023). "The co-cultured ovarian cancer cells show increased expression of PD-L1, VEGF, STAT3, IL-10, IL-6, B-cell lymphoma 2 (BCL2), and MDR1." (PMID 36757936, 2023). "Leptin has been shown to contribute to metastatic advancement of epithelial ovarian cancer by assisting cell migration and tissue invasion by binding to OB-Rb mediated via JAK/STAT3, MAPK, AKT, mTOR, RhoA/ ROCK, and MYPT1 signaling pathways." (PMID 34751020, 2022). "It is widely documented that persistently active STAT3 facilitates tumor progression in human PDAC and ovarian cancers in part by inducing anti-apoptosis and pre-metastatic niche formation, thus serving as a potential therapeutic target." (PMID 36324587, 2022). "It has been reported that STAT3 can be sequestered in the cytosol through binding with ARH-I, a maternally imprinted tumor suppressor involved in the regulation of ovarian cancer cell growth and dormancy." (PMID 35565270, 2022). "Another research has shown that NR1D1 inhibits activation of the JAK/STAT3 signaling pathway by upregulating the expression of SOCS3, thus suppressing ovarian cancer cell growth and inducing apoptosis." (PMID 35481240, 2022). "For instance, miR‐3666 targets STAT3 and modulates the activity of AK4, exhibiting a suppressive role in ovarian cancer." (PMID 34890108, 2022). "IL-6 increased the chemoresistance of ovarian cancer cells in vivo and in vitro, according to a recent study, by upregulating HIF-1 and STAT3 signaling." (PMID 36550571, 2022). "For instance, conditioned media derived from CD45−/CD31− adipose stromal cells, which are isolated from subcutaneous or visceral fat, was shown to activate the JAK2/STAT3 pathway via IL-6 and enhance migration in SKOV3 ovarian cancer cells." (PMID 35565396, 2022). "In cisplatin-resistant ovarian cancer cells, JAK/STAT3 signaling is hyperactive, with enhanced cell colony-forming capacity and metastasis capacity, which can be reduced by STAT3 inhibitors." (PMID 35559037, 2022). "It was found that miR-222-3p is enriched in epithelial ovarian cancer-derived exosomes, activates macrophage polarization toward TAMs of the M2 phenotype, and participates in the SOCS3/STAT3 pathway to promote cancer progression." (PMID 36439168, 2022).
ovarian carcinoma (continued). "Other amplified oncogenes frequently found in epithelial ovarian cancer were ERBB2, STAT3, PIK3C2B, CDK2, and CDK4, as well as SWI/SNF chromatin modification complex genes, including ARID1A and SMARCC1." (PMID 36430324, 2022). "The present study's findings demonstrate that by activating STAT3 signaling, TRIM47 functions as an oncogene in ovarian cancer." (PMID 36288633, 2022). "Differentially, in high-grade (G3, G4) ovarian cancer, STAT1, 2, 4, and 5A were highly expressed, while STAT3 and STAT5B were mostly lowly expressed." (PMID 36524006, 2022). "A similar axis also exists in ovarian cancer, but surprisingly, NORAD induces overexpression of signal transducer and activator of transcription 3 (STAT3) by interacting with miR-608 and functions as a tumor suppressor." (PMID 35387124, 2022). "Blockade of PDK4 suppressed activation of STAT3/AKT/NF-κB pathway to inhibit the cancer stem cell characteristics and glycolysis of ovarian cancer." (PMID 35543351, 2022). "This study analyzed TRIM47 biological function in human ovarian cancer and yielded experimental evidence that TRIM47 upregulation in ovarian cancer promotes cell proliferation, migration, and invasion by activating STAT3." (PMID 36288633, 2022). "According to one study, the expression of LINC00852 was highly up-modulated in ovarian cancer tissues, and it functioned as a ceRNA of miR-140-3p, promoting the expression of AGTR1 and activating the MEK/ERK/STAT3 signaling pathways." (PMID 35422758, 2022). "But it inhibited angiogenesis by restricting the p-STAT3 and NF-κB expression and reducing IL-6 and VEGF secreted by ovarian cancer cells." (PMID 35784750, 2022). "(H, I) Immunohistochemical analysis of IL20RA, p-STAT3, OAS1, and IL-18 in human primary ovarian cancer tissues (Pri) and paired peritoneal metastatic nodules (Met) (H) and quantification (I)." (PMID 34114949, 2021). "By inhibiting the signal transducer and activator of transcription 3 (STAT3) signaling pathway, several tumor suppressor miRNAs, including miR-92 and miR-503-5p, have been found to sensitize ovarian cancer cells to PTX." (PMID 34512721, 2021). "Whereas, SOCS3 silencing abolished the function of NR1D1 over-expression on ovarian cancer growth and JAK/STAT3 signaling pathway." (PMID 34330232, 2021). "Our study revealed that NR1D1 inhibited the activation of JAK/STAT3 signaling pathway through up-regulating SOCS3, thus suppressing proliferation and inducing apoptosis of ovarian cancer cells." (PMID 34330232, 2021). "Our study has shown that the inhibition of ERK 1/2, AKT and STAT3 activity significantly affected the expression of SNAIL 1 and SNAIL 2 as well as the levels of E-cadherin and N-cadherin in various ovarian cancer cell lines." (PMID 33478150, 2021). "A recent study examined the effect of curcumin against FSCN1 in the ovarian cancer cell line SKOV3 and found curcumin to inhibit STAT3 via the JAK/STAT3 signaling pathway." (PMID 34830909, 2021). "In the ovarian cancer mouse model, I-BET151 treatment inhibits the Stat3 signaling pathway, induces more CD3+ and CD8+ cells in the tumor, increases TNF-α and IFN-β mRNA levels in the tumor and mouse spleen, and induces an anti-tumor immune response." (PMID 34540687, 2021). "Lastly, CAFs are known to induce chemoresistance and promote ovarian cancer immune evasion, and CAF-intrinsic STAT3 signaling is essential for normal fibroblast transition into CAFs and CAF-mediated tumor progression." (PMID 34956861, 2021). "The discussed results indicate the universal character of STAT3 in the maintenance of both SNAIL 1 and SNAIL 2 expression in ovarian cancer cell lines, independently of cells’ origin, basal invasive potential or their resistance to cisplatin." (PMID 33478150, 2021). "In ovarian cancer, the activation of JAK2/STAT3 signaling is also correlated with enhanced EMT and a series of malignant phenotypes." (PMID 34895038, 2021).
ovarian carcinoma (continued). "In further study, we have decided to focus on the involvement of three effector proteins (ERK 1/2, AKT and STAT3) in the SNAILs-dependent induction of EMT markers (assessment of cadherins level), as well as in the chemoresistance of ovarian cancer cells." (PMID 33478150, 2021). "However, whether SOCS3/JAK/STAT3 is implicated in the role of NR1D1 in ovarian cancer remains not yet clear." (PMID 34330232, 2021). "In terms of anticancer activities, MEL has proved effective against different types of cancer cells such as ovarian cancer cells via the activation of death receptors and inhibition of JAK2/STAT3 pathway." (PMID 33919706, 2021). "In fact, it was demonstrated that MEL inhibited the ovarian cancer cells via induction of death receptors and inhibition of the JAK2L/STAT3 pathway." (PMID 33919706, 2021). "In conclusion, the novel small molecule STAT3 inhibitor, LLL12B, designed by AMLSD methodology shows excellent therapeutic potential in ovarian cancer cell lines." (PMID 33909625, 2021). "Herein, we explored the function of NR1D1 on the growth of ovarian cancer cells and the activation of SOCS3/JAK/STAT3 signaling pathway." (PMID 34330232, 2021). "Similar synergistic effects in vitro and in vivo have been reported in ovarian cancer with a combination of Gefitinib and a JAK/STAT3 inhibitor drug." (PMID 33544704, 2021). "In breast and ovarian cancer, the JAK2/STAT3 signaling pathway is related to the proliferation of cancer stem cells." (PMID 33788424, 2021). "In a previous study, treating ovarian cancer and rhabdomyosarcoma cells with anti-GP130 antibody or GP130 shRNA was found to inhibit STAT3 phosphorylation and/or cell survival, which is consistent with the results of this study." (PMID 34445405, 2021). "Also, curcumin may suppress fascin expression in ovarian cancer cells through STAT3 downregulation." (PMID 33213437, 2020). "Through the screen of differential genes and bioinformatics analysis, genes were closely related to ovarian cancer after downregulation of PADI2, such as STAT3 which was identified for further in-depth study on the occurrence and development of ovarian cancer." (PMID 32951601, 2020). "HE4 was found to activate STAT3 signaling and promote upregulation of the pro-angiogenic STAT3 target genes IL8 and HIF1A in immune cells, ovarian cancer cells, and endothelial cells." (PMID 32444701, 2020). "We verified the sequencing results of STAT3 phosphorylation levels in A2780 and SKOV3 ovarian cancer cells by western blot." (PMID 32951601, 2020). "Besides, although inhibiting the SRC pathway or STAT3 had negligible effects on each other, combined treatment with both JAKi and SRCi led to substantial inhibition of both pathways and exhibited much stronger antitumor activities against human ovarian cancer cells." (PMID 32895373, 2020). "The increased STAT3 expression and attenuated wingless-type MMTV integration site family (WNT) antagonist DKK1 were observed in CD83-overexpressed ovarian cancer cells." (PMID 32823589, 2020). "Altogether, nanocurcumin, given as a co-treatment with cisplatin has therapeutic potential in ovarian cancer models by inhibiting proliferation through downregulation of PI3K/Akt and JAK/STAT3 signaling pathways." (PMID 33536913, 2020). "In ovarian cancers, the expression of VEGF and its receptors VEGFR1 and VEGFR2 significantly correlate with pSTAT3 levels in patient samples, and STAT3 and VEGF have been shown to reciprocally regulate each other’s expression and activation in EOC models." (PMID 33335857, 2020). "In this study, we found that CD83 associated with MAP3K7 and activated MAPK cascades to further regulate FOXO1/p21/CDK2/CCNB1 and STAT3/DKK1 signaling pathways, thus activating proliferation and spheroid formation of ovarian cancer cells." (PMID 32823589, 2020).
ovarian carcinoma (continued). "In the present study, our formulation of curcumin nanoparticles was tested as co-treatment with cisplatin in a rat ovarian cancer model, with a focus on PI3K/Akt and JAK/STAT3 pathways." (PMID 33536913, 2020). "In this study, we demonstrated that cisplatin plus nanocurcumin has a synergistic effect by generating antiproliferation and apoptosis in ovarian cancer animal models by downregulation of PI3K/AKT and JAK/STAT3 signaling pathway." (PMID 33536913, 2020). "Downregulation of PADI2 in SKOV3 and A2780 ovarian cancer cells inhibited EMT-related markers and STAT3 phosphorylation." (PMID 32951601, 2020). "Together, the present study has established the role of nanocurcumin as adjunctive treatment to cisplatin in the ovarian cancer model through inhibition of TGF-β/PI3K/Akt and IL-6/JAK/STAT3 pathways." (PMID 33536913, 2020). "Ascites-derived ALDH+CD44+ tumour cell subsets endow stemness, metastatic and metabolic switch properties via PDK4-mediated STAT3/AKT/NF-κB/IL-8 signalling, suggesting PDK4 as a viable therapeutic molecular target for ovarian cancer management." (PMID 32390009, 2020). "Our results suggested that down-regulation of PADI2 combined with Olaparib played the role of anti-ovarian cancer by inhibiting EMT and STAT3 signaling pathway." (PMID 32951601, 2020). "Here, we demonstrate that cisplatin and nanocurcumin treatment suppressed the JAK/STAT3 pathway and reduced IL-6 expression, suggesting that the JAK/STAT3 pathway mediates the autocrine production of IL-6 in the ovarian cancer model." (PMID 33536913, 2020). "In epithelial ovarian cancer (EOC), TAMs derived exosomes loaded with miR-29a-3p and miR21-5p directly inhibit STAT3 signaling in CD4+T cells." (PMID 32992449, 2020). "More importantly, in ovarian cancer cells, a natural compound from Tripterygium wilfordii, Celastrol, promotes apoptosis by decreasing CD44 expression and STAT3 phosphorylation." (PMID 33335857, 2020). "Phosphorylated signal transducer and activator of transcription 3 (STAT3), which is found primarily in CD24+ tumor cells, promotes the self-renewal capacity of ovarian cancer CSCs, which also express higher mRNA levels of stemness genes." (PMID 33260974, 2020). "In epithelial ovarian cancer (EOC), exosomal miR-222-3p can be transferred to macrophages, down-regulating SOCS3, inducing phosphorylation of STAT3, and thus leading to polarization of the M2 macrophages." (PMID 32299469, 2020). "For example, NORAD silencing reduces ovarian cancer cell activity, migration, and invasion but induces cell apoptosis through the NORAD/miR-608/STAT3 axis." (PMID 32267831, 2020). "In turn, studies on ovarian cancer cells showed that MEL induced apoptosis through increased expression of death receptor (DR3, DR4, and DR6) and inhibition of STAT3 pathway." (PMID 31878020, 2019). "Our findings herein demonstrated that reduced PIK3R1 expression favors ovarian cancer tumorigenesis through AKT and AKT-independent activation of STAT3 signaling." (PMID 30755611, 2019). "Atezolizumab in combination with Bevacizumab inhibited the proliferation, migration, and invasion of cisplatin resistant ovarian cancer cell in vitro synergistically via Bevacizumab suppressing EMT and PD-L1 expression by targeting STAT3." (PMID 31105696, 2019). "Altogether, these observations imply that STAT3 promotes both EMT and cancer stemness as a transcription factor and is likely a major driving force in promoting metastasis in ovarian cancer." (PMID 31534498, 2019). "As we expected, CRL4 knockdown blocked STAT3 signaling activation and reduced BIRC3 expression in ovarian cancer cells, strongly suggesting that the upregulation of BIRC3 by CRL4 was also mediated by STAT3 signaling pathway in ovarian cancer." (PMID 30718461, 2019). "The precise interactions among STAT3, ALDH1A3, and CD44 in ovarian cancer require further assessment." (PMID 31534498, 2019).
ovarian carcinoma (continued). "To elucidate the functional role of STAT3 in regulating gene expression in ovarian cancer, we profiled SKOV3 STAT3 KO and WT cells using nascent RNA Bru-Seq (N =1), RNA-Seq (N =3) and MS proteomics (N =3)." (PMID 31534498, 2019). "In an ovarian cancer cell line pY-STAT3 co-localizes with TYK2 and JAK2 at focal adhesions, and hyperactive STAT3 was shown to promote cancer cell motility." (PMID 31694222, 2019). "A number of signaling pathways, including JAK/STAT3, AKT and ERK pathways, are constitutively activated and play important roles in the growth and progression of human ovarian cancers." (PMID 29986501, 2018). "In this study, we show a similar up-regulation of activated JAK2/STAT3 pathway, and concomitant significant increase in the expression of CSC-like markers in HEY and TOV21G ovarian cancer cell lines in response to paclitaxel treatment in vitro." (PMID 29682172, 2018). "To understand the effect of ruxolitinib on STAT3 phosphorylation, we incubated OVCAR-8, MDAH2774, and SKOV3 human ovarian cancer cells with increasing concentrations of ruxolitinib followed by Western blot analysis." (PMID 29849942, 2018). "We also compared the expression levels of STAT3, SITR3, HIF‐1α, GLUT1, LDHA, and HK2 of 44 ovarian cancer patient serums with 35 normal controls." (PMID 30094960, 2018). "We tested the expression levels of STAT3, SITR3, HIF‐1α, GLUT1, LDHA, and HK2 in 38 ovarian cancer patient tissues and 22 normal tissues." (PMID 30094960, 2018). "In this study, we first determined the abundance of STAT3, p-STAT3, and MMP-9 in ovarian cancer cells." (PMID 28859117, 2017). "This suggests that miR-519d has suppressive effects on ovarian carcinoma by downregulating RhoC, Bcl-2, cyclin D1, survivin, MMP2, MMP9, STAT3 and HuR expression." (PMID 28146423, 2017). "Ginsenoside Rb1, from P. notoginseng, has been reported to decrease the levels of p-STAT3 and SOCS3 in ovarian cancer cells, microglial cells, and obese mice." (PMID 29318137, 2017). "We found that STAT3 expression was inversely correlated with cDDP response, and that its low levels predicted an increased overall survival in DDP treated ovarian cancer patients up to 12 months from diagnosis." (PMID 26910918, 2017). "A role for leptin/LEPR in the survival of ovarian cancer cells was also demonstrated, similarly through the JAK2/STAT3 pathway, consistent with a previous study showing an alternate JAK2 inhibitor was able to induce apoptosis in ovarian cancer cells." (PMID 29212170, 2017). "STAT3 has been revealed to potentiate glucose metabolism and accelerate glycolysis by upregulating HK2 in breast, bladder, and ovarian cancer cells." (PMID 28445971, 2017). "The activation of signal transducer and activator of transcription 3 (STAT3), which is involved in cell proliferation and chemo-resistance, was significantly abrogated by ONA in ovarian cancer cells." (PMID 27404320, 2016). "In bladder and ovarian cancer cells, beyond the inhibition of STAT-3 expression and phosphorylation, it was demonstrated the reduction of STAT-3 into the nucleus." (PMID 27834913, 2016). "In summary, our data suggest ovarian cancer cells can transfer miR-222-3p to macrophages via exosomes, modulating the phenotype of TAMs by targeting the SOCS3 with involvement in the STAT3 pathway." (PMID 27172798, 2016). "In particular, we previously showed that STAT1 and STAT3 signaling was required for expression of IDO and PD-L1 in ovarian cancer cells." (PMID 27683036, 2016). "PLA performed in formalin-fixed paraffin-embedded ovarian cancer tissues clearly demonstrated the interactions between STIP1 and STAT3, STIP1 and JAK2, as well as STIP1 and HSP90 localized mainly in cytoplasm." (PMID 27409672, 2016). "In this current study we demonstrate that niclosamide not only targets the Wnt pathway, but it also targets the mTOR and the STAT3 pathways and specifically targets CD133+ CSCs and chemoresistant cells isolated from a PDX ovarian cancer model." (PMID 27888804, 2016).